SHH (sonic hedgehog signaling molecule)
Diseases named in the same sentence as SHH in open-access papers (continued):
Sharing a sentence is not in itself a finding about the gene and the disease.
brain tumor (51 papers, 2011 to 2026). "Aberrant regulation of SHH signaling pathways often causes neurodevelopmental diseases and brain tumors." (PMID 35573667, 2022). "The aberrant activation of SHH signaling often induces extensive hyperplasia and results in MB, a common malignant pediatric brain tumor, arising in the cerebellum." (PMID 35573667, 2022). "Nowadays, the SMO receptor is the primary target used for the development of SHH pathway inhibitors, and there are several ongoing clinical trials for different types of brain tumors." (PMID 36010607, 2022). "To this end, we initially utilized two well-established orthotopic brain tumor models with aberrant SHH signaling activation." (PMID 35831316, 2022). "We decided to start with the inhibition of the SHH pathway, because the involvement of the SHH pathway in the biology of pediatric brain tumors is well established." (PMID 31480400, 2019). "The embryonal brain tumor ETMR expressing LIN28A also displays additional features, such as WNT and SHH pathway activation." (PMID 40680886, 2025). "Our use of the v11b4/b6 brain tumor methylation classifier provided confident classifications for tumors as either MYC, SHH, or TYR AT/RT subgroups, even for extracranial RTs." (PMID 35912263, 2022). "This study aimed to investigate how SHH pathway inhibition affects both bulk GBM cells (GBMCs) and CD133 + GBM cells (GBM CSCs), with particular emphasis on the influence of astrocyte co-culture, which more closely mimics the brain tumor microenvironment." (PMID 40894044, 2025). "Besides epigenetic dysregulation, various signaling pathways are activated by genetic events in pediatric brain tumors, e.g., MAPK in LGG, SHH and WNT signaling in MB and ETMR, SHH and TYR in ATRT." (PMID 34830753, 2021). "A better understanding of the molecular characteristics involved in MB allowed to subdivide this pediatric brain tumor into four molecular subgroups: WNT, SHH, Group 3 and Group 4, with different molecular characteristics and clinical outcomes and thus to consider new therapeutic approaches." (PMID 29632646, 2018).
basal cell carcinoma (47 papers, 2009 to 2024). A carcinoma involving the basal cells. "Early events of basal cell carcinoma (BCC) tumorigenesis are triggered by inappropriate activation of SHH signaling, via the loss of Patched1 (Ptch1) or by activating mutations of Smoothened (Smo)." (PMID 31963474, 2020). "The SHH pathway has been implicated in the pathogenesis of multiple cancers including medulloblastoma, basal cell carcinoma, breast, colon and pancreatic ductal adenocarcinoma (PDAC)." (PMID 30645190, 2019). "Sonic Hedgehog (SHH) pathway dysregulation is implicated in basal cell carcinoma (BCC) development." (PMID 35505292, 2022). "i) The SMO (SMOOTHENED gene), at 7q32, a frizzled-class receptor belonging to the SONIC HEDGEHOG (SHH) pathway, associated with oncogenic conditions including basal cell carcinoma, malignant glioma, medulloblastoma, leukemia, and cancers of the breast, lung, pancreas, and prostate." (PMID 29725501, 2018). "In basal cell carcinoma, increased sonic hedgehog (SHH) has been linked to increased MYCN." (PMID 28358317, 2017). "Moreover, many cancers are associated with SHH signaling, such as basal-cell carcinoma, esophageal and stomach cancer, small-cell lung cancer and pancreatic adenocarcinoma." (PMID 23762282, 2013). "Of note, Basal Cell Carcinoma Signaling is closely related to Sonic Hedgehog (SHH) Signaling, which has been associated with the carcinogenesis of SCCs of the oral mucosa, uterine cervix, esophagus and lung, where it may have a role in mediating stemness via transcription factors like SOX2." (PMID 28787442, 2017). "Targeting SMO has emerged as a targeted treatment option for SHH-driven cancers including basal cell carcinoma and recurrent SHH-MB, demonstrating anti-tumor activity by suppressing SHH signaling." (PMID 39107797, 2024). "SHH-related genetic changes occur in multiple cancers, including 85% of basal cell carcinomas, 87% of medulloblastomas, and less often in breast, colorectal, gastric, pancreatic, non-small-cell lung, and ovarian cancers." (PMID 37046676, 2023). "Despite the importance of the SHH pathway in stemness and neoplasia, clinical development of vismodegib has failed in several cancer types except for basal cell carcinoma." (PMID 36034794, 2022). "Drugs targeting the SHH pathway have been developed, of which vismodegib and sonidegib have been approved by the Food and Drug Administration for treating basal cell carcinoma." (PMID 34513696, 2021). "The top categories sharing these criteria were signaling pathways including ECM-receptor interactions, basal cell carcinoma (dominated by mRNAs encoding WNT and SHH signaling factors) and NOTCH signaling." (PMID 32845239, 2020). "Vismodegib and sonidegib, inhibitors of the SHH pathway, were demonstrated to be efficacious in the treatment of basal cell carcinoma, and are FDA-approved therapies." (PMID 32957515, 2020). "Upstream of Gli, Vismodegib, a Smo inhibitor preventing activation of SHh target genes, has already been approved for basal cell carcinoma treatment, and is looking to expand its use to other cancers." (PMID 29416661, 2018). "Recent studies have reported SHH overexpression in basal cell carcinoma and lung squamous cell carcinoma." (PMID 23835807, 2013). "Type I HH pathway activation includes gain-of-function mutations in SHH that contribute to the formation of basal cell carcinoma, and heterozygous loss-of-function mutations in PTCH1 which cause Gorlin syndrome, basal cell cancers, and a range of other neoplasms including medulloblastoma." (PMID 36986819, 2023). "Sonic Hedgehog Protein (SHH) is the most important in the development of basal cell carcinoma." (PMID 35971151, 2022). "Ectopic expression of SHH is sufficient to induce basal cell carcinoma in mice." (PMID 29725501, 2018).
basal cell carcinoma (continued). "Ptch1 heterozygotes, which is a transmembrane receptor of Shh ligand as repressor of SHH signaling, are hypersensitive to ionizing radiation induced tumorigenesis and may develop tumors such as basal cell carcinoma." (PMID 23762282, 2013). "Gli2 is also expressed in many basal cell carcinomas, suggesting that these genes might also be involved in the development of PC, which could be consistent with its partial action as mediator of SHH signals." (PMID 22087285, 2011). "Indeed, a recent study showed that smoothened inhibitor-resistant basal cell carcinomas exhibit MAPK pathway enrichment concomitant with increases in ciliome gene mutations and reductions in primary cilia suggesting that the primary cilia control SHH-to-MAPK pathway switching." (PMID 37726268, 2023). "Gene set enrichment analyses (GSEA) upon that value featured ‘basal cell carcinoma’, dominated by WNT and SHH signaling factors, and ‘NOTCH signaling’ among the top three categories." (PMID 32845239, 2020). "The combination of SHH and EGF leads to a synergistically activated growth response in basal cell carcinoma and tumor-initiating pancreatic cancer cells both in vitro and in vivo." (PMID 32341755, 2020). "In the basal cell carcinoma pathway, 11 up-regulated genes, including GLI1, PTCH1, and SHH, were identified." (PMID 30770723, 2019). "The results of the present study also showed that the expression of GLI1, SHH, and PTCH1 involved in the basal cell carcinoma pathway was up-regulated in short-hair rabbits." (PMID 30770723, 2019). "Particularly, in basal cell carcinoma, the canonical WNT/beta-catenin signaling is required for SHH pathway-driven tumorigenesis." (PMID 27825128, 2016). "In mice, overexpression of SHH, activates SMO, GLI1 or GLI2 and promotes development of basal cell carcinoma like tumors." (PMID 23342114, 2013). "HHIP antagonizes all three of the hedgehog family of ligands (SHH, DHH and IHH) and has been shown to be down-regulated in numerous epithelial tumor types with the notable exception of basal cell carcinoma where it is upregulated." (PMID 20860831, 2010). "SHH inhibitors have been extensively investigated for the treatment of multiple cancers with widely varied clinical responses, ranging from FDA-approved therapy in advanced basal cell carcinoma to a detrimental effect in PDAC patients." (PMID 32957515, 2020). "Synergistic integration of SHH and EGF signaling has been identified as a critical step in oncogenic transformation, neural stem cell proliferation, and development of tumor types such as skin, prostate, pancreas, and basal cell carcinoma." (PMID 32341755, 2020). "As SHH signaling has been shown to be tumorigenic in various cancer types such as small cell lung cancer, colorectal adenocarcinoma, basal cell carcinoma, and even SCC itself, Rab23 was recognized as a negative regulator of carcinoma." (PMID 26716504, 2016).
gastric cancer (28 papers, 2010 to 2025). A primary or metastatic malignant neoplasm involving the stomach. "For instance, in a Japanese study on gastric cancer high SHH protein immunoreactivity assessed by IHC was associated with poor prognosis." (PMID 37964226, 2023). "The aim of this study was to explore molecular mechanisms underlying autocrine SHH signaling in gastric cancer cells." (PMID 27039174, 2016). "An increase in sonic hedgehog (SHH) expression and its activation in gastric carcinoma, especially H. pylori associated gastric carcinomas has been well established." (PMID 23671415, 2013). "SHH signaling has been implicated in the metastasis of gastric cancer and pancreatic adenocarcinomas." (PMID 20230186, 2010). "Increased SHH expression is associated with shorter survival in gastric cancer patients, and SHH could represent a useful biomarker or therapeutic target for this disease." (PMID 27039174, 2016). "However, the expression of CD44, a gastric cancer stem cell marker, was associated with improved survival in the group who received the SHH inhibitor suggesting that SHH inhibition may only be effective in those with high CD44 expression." (PMID 25784931, 2015). "ATF4 and SHH are significantly expressed in gastric cancer cell lines, as seen in our examination of its expression in Human Gastric Mucosal Epithelial Cells (GES1)." (PMID 36900220, 2023). "ATF4 is a downstream target of URB1 and is involved in the oncogenic role of URB1 in colorectal cancer.Our study demonstrated, for the first time, how transcriptional control of the SHH protein by ATF4 affects the development of gastric cancer." (PMID 36900220, 2023). "The biological function of ATF4 in vivo and in vitro by activating SHH has been established, and a more detailed molecular mechanism of ATF4 and SHH regulating the occurrence of gastric cancer should be investigated in the future." (PMID 36900220, 2023). "This study provides a new understanding of the critical underlying mechanism of ATF4 leading to the proliferation, invasion, and migration of gastric cancer cells through transcriptionally activating SHH." (PMID 36900220, 2023). "In a prior study, the KRAS proto-oncogene of the MAPK/ERK pathway was found to boost the transcriptional activity of GLI1 and the expression of SHH pathway target genes in gastric cancer." (PMID 36900220, 2023). "Mechanistically, rescue assays showed that ATF4 regulated gastric cancer cells’ proliferation and invasive ability through SHH." (PMID 36900220, 2023). "In recent years, several studies have reported that the SHH signaling pathway plays a critical role in the development and progression of many kinds of malignant tumours, such as gastric cancer and lung cancer." (PMID 34424425, 2021). "SHH signaling pathway is of pivotal importance in cell proliferation, tumor growth and gastric cancer directly." (PMID 31898580, 2019). "In gastric cancer tissue samples, we detected higher levels of SHH expression than in the normal tissues." (PMID 28399898, 2017). "In multivariate analyses, overall survival in gastric cancer was significantly shorter in cases with high SHH expression (HR = 1.734, 95 % CI: 1.109–2.713, P = 0.016)." (PMID 27039174, 2016). "Using gastric cancer cell lines, we measured SHH mRNA and protein expression, and studied the effects of SHH signaling on cell proliferation and SHH secretion." (PMID 27039174, 2016). "In conclusion, our data suggested that SHH pathway was essential for maintenance of CSLCs in human gastric cancer." (PMID 21394208, 2011).
gastric cancer (continued). "Results showed that tumorsphere cells from gastric cancer specimen also had chemoresistance and tumorigenic capacity, moreover SHH pathway blocking reduced the chemoresistance of tumorsphere cells and enhanced tumor response to drugs in vivo." (PMID 21394208, 2011). "It has been reported that SHH can promote motility and invasiveness of gastric cancer cells, suggesting the involvement of SHH signaling in the metastasis of gastric cancer." (PMID 20230186, 2010). "We devised a series of rescue studies to show whether ATF4 controls the proliferation and invasion capacity of gastric cancer cell lines through SHH protein." (PMID 36900220, 2023). "It is yet unknown how ATF4 contributes to gastric cancer on a cellular level or whether it stimulates the SHH protein through transcription." (PMID 36900220, 2023). "The findings above imply that ATF4 may control gastric cancer cell invasion and proliferation through changing the SHH protein." (PMID 36900220, 2023). "However, on the contrary, a Korean study involving larger cohort of gastric cancer patients, revealed longer overall survival in a group with overexpression of SHH demonstrated by IHC staining." (PMID 37964226, 2023). "Furthermore, ATF4 regulates the proliferation, invasion, and migration ability of gastric cancer cells through transcriptional activation of SHH." (PMID 36900220, 2023). "These could be taken as biomarkers to predict gastric cancer progression and determine benefit after SHH antagonist treatments." (PMID 31979397, 2020). "The change of SHH expression induces gastric cancer development." (PMID 31979397, 2020). "In gastric cancer, SHH-triggered tumor cell invasion was associated with the activation of the TGF-β signaling pathway, and the blockage of the TGF-β signaling inhibited SHH-induced cell motility." (PMID 29695137, 2018). "Overexpression of SHH in human gastric cancers has also been reported." (PMID 28427431, 2017). "Intriguingly, loss of Gal-1 in gastric cancer cells resulted in a lack of SHH expression, leading to Hh inactivation, which downregulated SMO and Gli-1." (PMID 27835885, 2016). "The AGS and SGC-7901 gastric cancer cell lines expressed SHH mRNA and protein." (PMID 27039174, 2016). "SHH protein expression in gastric cancer tissue was significantly higher compared with that in normal gastric tissue (P < 0.001), and the increased expression was significantly associated with pT staging (P = 0.004), pN staging (P = 0.018), pM staging (P = 0.006), and pTNM staging (P < 0.001)." (PMID 27039174, 2016). "To determine whether SHH pathway could be involved in the gastric CSCs characteristics of tumorsphere cells from gastric cancer tissue, we utilized primary gastric cancer samples to analyze the functional aspects of SHH pathway in gastric CSLCs." (PMID 21394208, 2011). "Finally, we utilized primary gastric cancer samples to analyze the functional aspects of SHH pathway in gastric CSLCs." (PMID 21394208, 2011). "Finally, we isolated the tumorspheres from gastric cancer specimen, these cells also had chemoresistance and tumorigenic capacity, and SHH pathway maintained the gastric CSLCs characteristics of tumorsphere cells from primary tumor samples." (PMID 21394208, 2011). "Our data suggested that apatinib exhibited inhibitory effects on GCSCs by suppressing SHH pathway both in vitro and in vivo, thus providing new insights into the therapeutic application of apatinib in GCSC suppression and advanced gastric cancer treatment." (PMID 34350176, 2021). "Since multiple studies report the involvement of SHH in gastric cancer, it is possible that GLI3 is mediating SHH-induced effects." (PMID 32245491, 2020). "On the other hand, SHH signaling pathway regulates the occurrence and development of tumors via MAPK/ERK signaling pathway, such as liver cancer, gastric cancer, and non-small cell lung cancer." (PMID 30568656, 2018).
gastric cancer (continued). "SHH was mainly expressed in the cytoplasm and GLI1 protein was predominantly localized to the nucleus and cytoplasm in gastric cancer cells." (PMID 28399898, 2017). "ATF4 is not identified to regulate SHH, inhibiting the Sonic Hedgehog signaling pathway and preventing the onset and spread of gastric cancer." (PMID 36900220, 2023). "Compared to the surrounding non-cancerous tissues, the expression of ATF4 and SHH in stomach cancer tissues was greater, and the correlation between ATF4 and SHH was detected in 80 clinical gastric cancer tissues by immunohistochemistry score." (PMID 36900220, 2023). "In order to examine whether Hh signaling pathway was activated in gastric cancer, we determined the expression of SHH and GLI1 in 90 pairs of gastric cancer tissue and adjacent normal tissue samples by immunohistochemistry." (PMID 28399898, 2017). "It suppresses the epithelial-mesenchymal transition through the SHH-GLI family zinc finger 1 (GLI1) pathway in hepatocellular carcinoma and through downregulation of the methylcrotonyl-CoA carboxylase subunit 1 (MCCC1) expression in malignant melanoma and gastric cancer." (PMID 40787625, 2025). "In addition to OSCC cancer stem cells, gastric cancer stem cells, that were sorted based on CD44+ CD24+ surface expression, showed 80-fold higher GLI3 mRNA expression than the CD44lo CD24lo phenotype which positively correlated with mRNA expression of SHH and PTCH1." (PMID 32245491, 2020). "However, the autocrine SHH pathway has not been described in gastric cancer." (PMID 27039174, 2016).